MIR550B2 (microRNA 550b-2)
Synonyms: hsa-mir-550b-2
Gene: MicroRNA gene on chromosome 7 (32,732,981 to 32,733,077, reverse strand). Ensembl gene ENSG00000283461.
Gene Ontology:
Biological process: miRNA-mediated post-transcriptional gene silencing
Cellular component: RISC complex